LINC01090 (long independently transcribed non-coding RNA 1090)
Gene: Long non-coding RNA gene on chromosome 2 (187,711,775 to 188,384,400, reverse strand). Ensembl gene ENSG00000231689.
Diseases named in the same sentence as LINC01090 in open-access papers:
LINC01090 is named in the same sentence as 1 disease in open-access papers, as found by Europe PMC text mining. Sharing a sentence is not in itself a finding about the gene and the disease.
LINC01090 shares sentences with these, for which no sentence is quoted: post-traumatic stress disorder (1 paper).